SLC12A3 (solute carrier family 12 member 3)
Diseases named in the same sentence as SLC12A3 in open-access papers (continued):
Sharing a sentence is not in itself a finding about the gene and the disease.
Gitelman syndrome (continued). "Gitelman syndrome, also known as familial hypokalemia-hypomagnesemia, is well known by nephrologists and is due to a mutation of the NCCT/SLC12A3 gene encoding the Na-Cl cotransporter sensitive to thiazide diuretics located at the distal convoluted tubule." (PMID 37563694, 2023). "This research uncovers a novel combination of SLC12A3 and PDX1 gene mutations in a Gitelman Syndrome patient, revealing intricate genetic factors that potentially disrupt glucose metabolism and shedding light on familial diabetes links." (PMID 38333726, 2023). "We then described the different genetic and biological effects of SLC12A3 in Gitelman syndrome and diabetic kidney disease." (PMID 35591852, 2022). "In Gitelman syndrome, loss-of-function mutations in SLC12A3 cause impaired NCC-mediated Na+ reabsorption." (PMID 35894287, 2022). "Gitelman syndrome is caused by biallelic mutations in the SLC12A3 gene, encoding the NCC, of which the expression is restricted to the DCT." (PMID 35137195, 2022). "Gitelman syndrome (GS, OMIM #263800) is a rare autosomal recessive disorder due to homozygous or compound heterozygous variants in the SLC12A3 gene which encodes the thiazide-sensitive Na+/Cl− cotransporter." (PMID 35327948, 2022). "Gitelman syndrome (GS) and Bartter syndrome (BS) type III are both rare, recessively inherited salt-losing tubulopathies caused by SLC12A3 and CLCNKB mutations, respectively." (PMID 33807568, 2021). "We have identified a novel deletion of the SLC12A3 gene and discussed the appropriate hypoglycemic drugs in Gitelman syndrome (GS) patients with type 2 diabetes." (PMID 34348722, 2021). "Patients with Gitelman syndrome, which is caused by mutations in the SLC12A3 gene encoding the thiazide‐sensitive NCC (NCC; OMIM: 263800), suffer from renal Na+ wasting, hypokalaemia, metabolic alkalosis and hypomagnesaemia." (PMID 32603001, 2021). "Gitelman syndrome (GS, OMIM 263800) is a genetic congenital tubulopathy associated with salt loss that is caused by defects in the sodium chloride cotransporter (NCCT, encoded by SLC12A3) with an autosomal recessive inheritance pattern." (PMID 33996672, 2021). "This is evidenced by the phenotype displayed by patients with Gitelman’s syndrome, a genetic disease caused by inactivating mutations in the SLC12A3 gene that encodes NCC." (PMID 33192599, 2020). "Gitelman syndrome is associated with mutations of SLC12A3 (solute carrier family 12 member 3) gene, which locates on chromosome 16q13 and encodes the thiazide-sensitive Na-Cl cotransporter (NCCT) of distal convoluted tubule (DCT)." (PMID 32758178, 2020). "Gitelman syndrome is the most common inherited tubular disease and results from mutations in the SLC12A3 gene encoding NCC." (PMID 32789612, 2020). "Till now, there are more than 400 varieties of SLC12A3 related to Gitelman syndrome have been reported." (PMID 32758178, 2020). "How the Arg913Gln variation of SLC12A3 gene influence in the pathophysiology of diabetic nephropathy in individuals with Type 2 Diabetes Mellitus and Gitelman syndrome?" (PMID 31660880, 2019). "Inclusion criteria for this review were: 1) Studies that analyzed the SLC12A3 gene in individuals with Type 2 Diabetes and Gitelman Syndrome." (PMID 31660880, 2019). "Loss-of-function mutations in SLC12A3, SLC12A1, and KCNJ1 genes, essential for normal renal NaCl reabsorption, cause Bartter’s and Gitelman’s syndromes." (PMID 29495593, 2018). "A presumptive diagnosis of Gitelman syndrome (GS) was then made and the patient's peripheral blood mononuclear cells were subjected to sequence analysis of the SLC12A3 gene, which encodes a thiazide-sensitive sodium-chloride cotransporter." (PMID 25140267, 2014). "Gitelman syndrome is a familial autosomal recessive disorder characterized by metabolic alkalosis, hypocalciuria, normotension, and renal wasting of potassium and magnesium due to defects in SLC12A3." (PMID 40520344, 2025).
Gitelman syndrome (continued). "Gitelman syndrome (GS) is a rare hereditary electrolyte disorder caused by mutations in the SLC12A3 gene, which encodes the thiazide-sensitive sodium-chloride cotransporter (NCC) in the distal convoluted tubule." (PMID 39792715, 2025). "Gitelman syndrome (GS) is an autosomal recessive renal tubular disorder caused by a pathogenic variant in the SLC12A3, which encodes the thiazide-sensitive Na-Cl cotransporter (NCC)." (PMID 40070587, 2025). "Gitelman syndrome is characterized by hypokalemia, metabolic alkalosis, hypomagnesemia, hypocalciuria, and renin-angiotensin-aldosterone system (RAAS) activation, and is caused by variants in the SLC12A3 gene." (PMID 37377595, 2023). "Similarly, to unravel the loss-of-function mechanism of missense variants in Gitelman syndrome (GTLMNS; OMIM: #263800), a minigene assay was used to show that several exonic missense variants in the SLC12A3 affect mRNA splicing." (PMID 36672937, 2023). "Therefore, clinical diagnosis of Gitelman syndrome was made, and the identified SLC12A3 variations were predicted to contribute clinical features of Gitelman syndrome." (PMID 32758178, 2020). "Gitelman syndrome (GS) is a rare salt-losing tubulopathy caused by an inactivating mutation in the SLC12A3 gene, encoding the thiazide-sensitive sodium chloride cotransporter (NCC)." (PMID 33238651, 2020). "Gitelman syndrome (GS) is a rare autosomal recessive renal tubular disease, caused by mutations in the SLC12A3 gene, which encodes the renal thiazide-sensitive Na/Cl cotransporter (NCCT) in the distal renal tubule." (PMID 30558554, 2018). "Gitelman syndrome (GS) is an inherited renal tubular disorder characterized by hypokalemic alkalosis and hypomagnesemia, due to biallelic pathogenic variants in the solute carrier family 12 member 3 (SLC12A3) gene encoding a sodium-chloride (Na-Cl) cotransporter (NCC)." (PMID 39934873, 2025). "Gitelman syndrome (GS) is a rare autosomal recessive renal tubular disease that generally occurs in adolescence or adulthood, mainly due to mutations in the SLC12A3 gene, which leads to abnormalities in the thiazide sensitive sodium chloride cotransporter (NCCT) in the distal convoluted tubules." (PMID 37327293, 2023).
Hypertension (90 papers, 2006 to 2025). The presence of chronic increased pressure in the systemic arterial system. "SLC12A3 is considered to encode a renal thiazide-sensitive sodium-chloride cotransporter, recognized as the target for thiazide diuretics to control high blood pressure." (PMID 38373964, 2024). "This study aimed to examine the association between SLC12A3 polymorphisms and renal function in Chinese patients with hypertension." (PMID 35801212, 2022). "We aimed to investigate the association between SLC12A3 gene polymorphisms and renal function in patients with hypertension." (PMID 35801212, 2022). "As this is the first study to report the association between SLC12A3 polymorphisms and renal function in patients with hypertension, further studies are still needed to further confirm our findings." (PMID 35801212, 2022). "Further studies are needed to clarify the relationship between SLC12A3 polymorphisms, sodium intake and excretion, and renal function decline in patients with hypertension." (PMID 35801212, 2022). "Studies of SLC12A3 suggested that its genetic variants and rare mutations impact the development of hypertension and T2DM and/or nephropathy in Asian populations, which is consistent with the results of our study." (PMID 32600448, 2020). "The SLC12A3 mutations produce clinically significant blood pressure reduction and protect from development of hypertension." (PMID 31464655, 2019). "Gene SLC12A3 encodes a renal thiazide-sensitive sodium-chloride cotransporter, and the protein is the target for thiazide diuretics which is used for treating high blood pressure." (PMID 31464655, 2019). "Our previous work also demonstrated a close association between SLC12A3 polymorphism and human hypertension in Mongolians, both within random and pedigree populations." (PMID 29661184, 2018). "The second possibility is that recent studies have shown that in addition to hypertension and hyperlipidemia, SLC12A3 is also associated with type II diabetes and obesity." (PMID 29661184, 2018). "SLC12A3, which has an established role in regulating osmotic balance, is associated with hypertension in human and shows differential expression in kidney tissue between sticklebacks kept in freshwater or sea water." (PMID 27138043, 2016). "In Gitelman syndrome, loss of function mutations of SLC12A3 lead to salt loss and hypokalemia, while, on the contrary, its constitutive activation by upstream regulatory kinases or E3 ubiquitin ligases cause hypertension hyperkalemia in Gordon’s syndrome." (PMID 39936967, 2025). "In the participants with YOH (cohort 1) and treatment-naïve hypertension (cohort 2), SLC12A3 rs16963397 C/C or C/G polymorphisms, SLC12A3 rs13334864 C/C or C/T polymorphisms, and SLC12A3 rs7187932 A/A or A/G polymorphisms were associated with higher eGFR than their counterparts." (PMID 35801212, 2022). "Fourthly, some studies showed that the gene encoding solute carrier family 12 member 3 (SLC12A3) is a typical candidate related with arterial hypertension in obese subjects, and its under expression could prevent this comorbidity in obese subjects." (PMID 35059043, 2022). "SLC12A3 polymorphisms are associated with renal function in Chinese patients with hypertension." (PMID 35801212, 2022). "Furthermore, SLC12A3 rs16963397 and rs13334864 polymorphisms were associated with renal function decline in participants with hypertension." (PMID 35801212, 2022). "The Arg904Gln variant of SLC12A3 may increase the risk of EH (essential hypertension), which indicates that the Arg904Gln variant may be a functional gain mutation." (PMID 34046503, 2021). "SLC12A3 gene had been identified and speculated that, its genetic variants and rare mutations will impact the development of hypertension, although more mutations are need to verify." (PMID 29661184, 2018). "Thus, it is possible that the genetic polymorphisms of SLC12A3 might be associated with hypertension via modulating an individual’s serum lipid levels." (PMID 28166833, 2017).
Hypertension (continued). "Carriers of single heterozygous pathogenic variants in SLC12A1, SLC12A3, and KCNJ1 were shown to have a reduced prevalence of hypertension and for SLC12A3 also in lower serum potassium levels." (PMID 37612755, 2023). "SLC12A3 rs16963397, rs13334864, and rs7187932 polymorphisms were found to be associated with eGFR in YOH and treatment-naïve hypertension." (PMID 35801212, 2022). "Our study is the first to investigate the link between SLC12A3 genetic variations and renal function decline in patients with hypertension." (PMID 35801212, 2022). "Variants of the AT1 receptor of angiotensin II (AGTR1) and other genetic polymorphisms such as the G protein-coupled receptor kinase 4 (GRK4) and solute carrier family 12 member 3, SLC12A3, have been related to arterial hypertension and atherosclerosis." (PMID 32714484, 2020). "Within Mongolian population, two previous reports also demonstrated the close relationship between SLC12A3 and hypertension, both with random case-control sample and pedigree cohort." (PMID 29661184, 2018). "Previous work also demonstrated important roles of genetic variants of SLC12A3 gene on human CVD, hypertension and other diseases in Mongolian population." (PMID 29661184, 2018). "For NCC, its encoding gene SLC12A3 is specifically expressed in the apical membrane of the DCT cells of kidney, whose genetic variants and mutations show closely relationship to individual’s blood pressure and/or hypertension." (PMID 36305246, 2022). "Hypertension is associated with loss-of-function mutations in genes that regulate normal renal salt reabsorption in the TALH and DCT including the Na-K-2Cl co-transporter gene; the inward rectifier K+ channel gene ROMK; and the Na-Cl co-transporter gene SLC12A3." (PMID 26727517, 2016). "Therefore, thiazide-type diuretics are among the most widely used agents in the management of hypertension and CVD by blocking SLC12A3." (PMID 35591852, 2022). "Eventually we identified a set of SNPs and environmental factors: rs5805 in the SLC12A3, rs12654264 in the HMGCR, rs2065412 and rs414936 in the ABCA1, rs96418 in the ZPR1 gene, waistline, degree of education, exercise frequency, hypertension, and the intake of meat." (PMID 32600448, 2020). "We find that hydrochlorothiazide targets the sodium-chloride symporter pathway (e.g., SLC12A3) and spironolactone targets the mineralocorticoid receptor pathway (e.g., NR3C2), both in the hypertension disease module following by the Complementary Exposure category." (PMID 30867426, 2019). "By using thiazide to inhibit the SLC12A3 gene activity, a negative sodium balance, may be induced with great health benefit in preventing hypertension and CVD." (PMID 35591852, 2022). "(g) TZD-insensitive hypertension (“nonresponders” in humans): The TZD target should not be exposed/present in hypertensive models insensitive to TZD arterial pressure reduction (Diuresis and Plasma Volume, [Na+/Cl− Cotransporter (NCC; SLC12A3)]; Constrictor Pathways In Vivo)." (PMID 31543812, 2019).
Hypokalemia (66 papers, 2014 to 2026). An abnormally decreased potassium concentration in the blood. "Persistent hypokalemia, hypomagnesemia, and metabolic alkalosis led to genetic testing, which identified compound heterozygous pathogenic variants in SLC12A3, confirming GS." (PMID 41958666, 2026). "Persistent hypokalemia, hyperaldosteronism, and hypomagnesemia in subsequent disease course, as well as mutations of the SLC12A3 gene, confirmed the diagnosis of GS." (PMID 41867936, 2026). "Diagnosis is based on biochemical findings - persistent hypokalemia, hypomagnesemia, and low urinary calcium excretion - and is confirmed by genetic testing for SLC12A3 mutations." (PMID 40525024, 2025). "Laboratory examinations unveiled hypokalemia with renal potassium wasting, hypomagnesemia, metabolic alkalosis, hypocalciuria, and gene sequencing revealed a homozygous mutation in SLC12A3 (c.179C > T [p.T60M])." (PMID 39183425, 2024). "Loss of function mutations in SLC12A3 (encoding NCC), result in autosomal recessive Gitelman syndrome characterized with hypokalemia, hypomagnesemia, metabolic alkalosis and hypercalciuria which resembles the effects of chronic thiazide diuretic use." (PMID 37394514, 2023). "Here, we report our experiences with a patient that presented with hypokalemia and proteinuria; genetic analysis revealed a new homozygous mutation in the SLC12A3 gene." (PMID 30340552, 2018). "GS is an autosomal recessive tubulopathy associated with hypokalemia, metabolic alkalosis, hypomagnesemia, and hypocalciuria, resulting from mutations in the SLC12A3 gene encoding the thiazide-sensitive sodium−chloride cotransporter localized to the distal convoluted tubule." (PMID 40525024, 2025). "Moreover, further genetic testing of hypokalemia-related genes revealed reported pathogenic compound mutations in the SLC12A3 gene, so the clinical diagnosis of GS can be identified." (PMID 37131142, 2023). "Moreover, our findings suggested that 24-h sodium urine excretion may be a predictor of early NCC dysfunction and SLC12A3 heterozygous individuals may be more susceptible to diuretic-induced hypokalemia." (PMID 30413979, 2019). "Due to persistence of hypokalemia, SLC12A3 whole genome sequencing was performed, showing a heterozygous C to T base pair substitution at position 965 in gene SLC12A3." (PMID 33763274, 2021). "SLC12A3 heterozygosity is often reported in patients presenting with hypokalemia, and as far as blood pressure goes they may have an intermediate phenotype between normal and GS." (PMID 36938092, 2023). "GS caused by SLC12A3 sequence variations is characterized by hypochloremic metabolic alkalosis, hypomagnesemia, RAAS activation with normal or low blood pressure, salt loss, and hypokalemia." (PMID 35327948, 2022). "I-1 also carried both heterozygous mutation in SLC12A3 and CLCNKB, which may explain his hypokalemia." (PMID 33807568, 2021). "During the stress of hypokalemia, a serine-threonine kinase cascade within the distal convoluted tubule (DCT) activates the thiazide-sensitive NaCl cotransporter (NCC; SLC12A3) via phosphorylation." (PMID 40493421, 2025). "In the present study, a patient with persistent hypokalemia was diagnosed with GS and T2DM by gene SLC12A3 analysis and oral glucose tolerance test (OGTT), respectively." (PMID 32702863, 2020).
Hypomagnesemia (32 papers, 2016 to 2026). An abnormally decreased magnesium concentration in the blood. "The observation that mutations in SLC12A3, KCNJ10, and KCN16 inhibit NCC activity and cause hypomagnesemia illustrates that reduced NCC activity affects magnesium reabsorption." (PMID 35195759, 2022). "We describe an inbred family with coexisting hypomagnesemia and hyperuricemia caused by simultaneous homozygous mutations in SLC12A3 and CLCNKB gene." (PMID 33807568, 2021). "CBS should be differentiated with GS (OMIM #263800), GS is a milder disease frequently associated with hypomagnesemia and hypocalciuria, caused by dysfunction of SLC12A3 gene encoding the sodium chloride co-transporter NCCT in the distal convoluted tubule." (PMID 31409296, 2019). "Inactivating mutations in SLC12A3 cause Gitelman syndrome, the most frequent cause of hereditary hypomagnesemia and characterized by hypokalemic metabolic alkalosis with hypomagnesemia and hypocalciuria." (PMID 29686978, 2018). "For the present pedigree, while both I-2 and II-4 carry the same dual homozygous mutations in SLC12A3 and CLCNKB, II-2 had hypomagnesemia, gout and CPPD, whereas II-4 had normal magnesemia and kidney stones." (PMID 33807568, 2021).
Hypocalciuria (30 papers, 2014 to 2025). An abnormally decreased calcium concentration in the urine. "Although sex, genotypes, or the number of SLC12A3 mutant alleles did not predict severity or response to treatment, hypocalciuria and hypomagnesemia were useful markers to differentiate GS from classical type 3 BS." (PMID 32784543, 2020).
Bartter syndrome (20 papers, 2014 to 2025). "Despite the fact that the causative gene (SLC12A3) was discovered in 1996, Gitelman syndrome has been confused with a subtype of Bartter syndrome, leading to misdiagnoses for many years." (PMID 34768847, 2021). "For the 19 patients without SLC12A3 mutation, some underwent further genetic test or clinical inspection, and final diagnosis of Bartter syndrome (BS), hypokalemic periodic paralysis and primary aldosteronism were given." (PMID 30319542, 2018). "Moreover, mutations in the SLC12A3 intron or other genes, like the CLCNKB gene linked with Bartter syndrome, might be alternative molecular defects." (PMID 38333726, 2023).
Hypercalciuria (9 papers, 2015 to 2025). "Given the presence of hypercalciuria was not consistent with Gittelman syndrome, deletion/duplication testing of SLC12A3 was not pursued." (PMID 33602924, 2021).